VDR (vitamin D receptor)
Diseases named in the same sentence as VDR in open-access papers (continued):
Sharing a sentence is not in itself a finding about the gene and the disease.
ovarian carcinoma (continued). "VDR is weakly expressed in normal ovarian cells, but it is highly expressed in ovarian cancer cell lines and tumor tissues." (PMID 30157901, 2018). "Consistently, the expression of VDR is inversely correlated with that of COX-2 in malignant breast cell lines and ovarian cancer tissues, supporting the role of the calcitriol–VDR axis in suppressing the expression of COX-2 and production of PGs." (PMID 29657326, 2018). "We first analyzed the expression level of VDR in CSCs and their corresponding bulk cancer cells of four ovarian cancer cell lines." (PMID 29581858, 2018). "Our findings suggest that calcitriol targets ovarian CSCs via the VDR-mediated inhibition of the Wnt pathway, and therefore displays potential therapeutic utility in ovarian cancer treatment." (PMID 29581858, 2018). "To this end, we downregulated VDR expression in the ovarian cancer cell line 2008, treated cells with calcitriol, and determined the CSC populations characterized by CD44+CD117+ or ALDH+." (PMID 29581858, 2018). "Dihydrotestosterone upregulates the expression of VDR and hence the activity of 1,25 (OH)D3, resulting in a growth inhibition of the human ovarian cancer cell line OVCAR-3." (PMID 29113037, 2017). "Different studies have shown that VDR expression is increased in ovarian cancer, indicating an endogenous response to tumor progression." (PMID 29113037, 2017). "A cross-link between VDR and androgen receptor, an important stimulator of growth in human ovarian cancer cells, has been postulated." (PMID 29113037, 2017). "In conclusion, our report shows that the VDR is expressed across a spectrum of germline-derived tumors, from teratocarcinoma cells to ovarian cancer cells, and supports our proposal that vitamin D3 is an inhibitor of their proliferation." (PMID 27091127, 2016). "To learn more about the potential role of vitamin D3 in cancerogenesis, we evaluated the expression and functionality of the vitamin D receptor (VDR) and its role in metastasis of ovarian cancer cells and of murine and human teratocarcinoma cell lines." (PMID 27091127, 2016). "The high concentrations of the vitamin D receptor were demonstrated in ovarian cancer cells, and 1α,25(OH)2D3 has been shown to inhibit cell proliferation and induce apoptosis in ovarian cancer cell lines." (PMID 27548154, 2016). "To better address the role of vitamin D3 in germline-derived tumors, we investigated the expression and potential role of the vitamin D3 receptor (VDR) in ovarian cancer and teratocarcinoma cells." (PMID 27091127, 2016). "The presence of VDR in normal ovarian epithelium, in human ovarian tumors, and in human ovarian cancer cell lines has been demonstrated." (PMID 26000308, 2015). "Distribution of VDR genotype was significantly different (χ2 = 4.24, p value < 0.05) in ovarian cancer patients from that in controls." (PMID 23705897, 2013). "Another study about ovarian cancer has shown the synergistic effect of VDR and RBP." (PMID 40732992, 2025). "VDR may inhibit androgen receptor expression, commonly found in ovarian tumors, and act as an antagonist for growth-promoting androgens in ovarian cancer cells." (PMID 38698459, 2024). "In related research, VD has exhibited inhibitory effects on the progression of various cancer, such as melanoma 87, Kaposi's sarcoma 88, oral squamous cell carcinoma 89, and ovarian cancer 90, by modulating the Wnt/β-catenin signaling pathway through its interaction with VDR." (PMID 38230221, 2024). "Experimental research in ovarian cancer models shows that vitamin D metabolites inhibit ovarian cancer cell growth, increase apoptosis and the expression of the vitamin D receptor, and delay the development and progression of chemically induced ovarian tumors in vivo and in vitro." (PMID 38754871, 2024).
ovarian carcinoma (continued). "As TOPORS-AS1 is a target for VDR, it has been suggested that the inhibitory effect of VDR in ovarian cancer cells could be mediated through TOPORS-AS1." (PMID 36145244, 2022). "TOPORS-AS1 may be stimulated by VDR to exert its action as a tumor suppressor in ovarian cancer through disruption of Wnt/β-catenin signaling." (PMID 35328609, 2022). "Moreover, the results of in vivo and in vitro studies have suggested that 1,25(OH)2D3 and VDR inhibited the spread of ovarian cancer." (PMID 34208589, 2021). "Of note, an inverse correlation between VDR expression and cyclooxygenase-2 expression has been also identified in ovarian cancer tissues and malignant breast cancer cell lines, supporting the role of 1,25(OH)2D3-VDR axis in the inhibition of cyclooxygenase expression and prostaglandins production." (PMID 34208589, 2021). "Taken together, these findings suggest that TOPORS-AS1 may behave like a tumor suppressor in ovarian cancer through interrupting the Wnt/β-catenin signaling and that VDR upregulates the expression of TOPORS-AS1." (PMID 33820921, 2021). "We also suggest that modulation of VDR and RORγ activities with their agonists could affect ovarian cancer cell behavior, suggesting their usefulness as potential targets in ovarian cancer therapy." (PMID 33227893, 2020). "Through immunohistochemistry, VDR staining was examined in 156 ovarian cancer samples." (PMID 32572587, 2020). "In addition, in vivo and in vitro studies have suggested that 1,25(OH)2D and VDR help inhibit the spread of ovarian cancer to the omentum." (PMID 32024052, 2020). "Therefore, we performed co-immunofluorescence of H3K4me3 and VDR in selected ovarian cancer specimens." (PMID 32245092, 2020). "The vitamin D receptor is present in normal ovarian epithelium and ovarian cancer cells." (PMID 32024052, 2020). "Furthermore, cooperation between VDR and the androgen receptor, both of which regulate ovarian cancer cell growth, has been demonstrated." (PMID 32024052, 2020). "Similarly to VDR, we also showed lower RORγ expression in ovarian cancers in comparison to normal tissues." (PMID 33227893, 2020). "However, increasing evidence suggests that vitamin D and VDR play a pivotal role in the development of ovarian cancer." (PMID 32572587, 2020). "We further examined the co-expression of VDR and H3K4me3 in ovarian cancer tissues." (PMID 32245092, 2020). "In this study, we tested whether VDR, RORγ, and RORα are expressed in ovarian cancers, and we correlated their expression with clinico-pathological data, including patient survival time." (PMID 33227893, 2020). "Our result displayed obvious co-expression of VDR and H3K4me3 in ovarian cancer." (PMID 32245092, 2020). "Therefore, we explored the relation between ovarian cancer and individual SNPs, VDR 3′ end haplotypes, and estimated GC phenotypes by predicted 25(OH)D strata." (PMID 25368842, 2014). "Overall, we observed that some, but not all, genetic variation at the 3′ end of the VDR gene is associated with a modestly increased risk of ovarian cancer." (PMID 25368842, 2014). "Therefore, VDR may stimulate TOPORS-AS1 to exert its action as a tumor suppressor in ovarian cancer through disruption of Wnt/β-catenin signaling." (PMID 35328609, 2022). "Research involving prostate and ovarian cancer propose the potential role of androgen receptor-coregulators, especially ARA70 (androgen receptor-associated protein 70), which seems to be necessary for both androgen receptor (AR) and VDR transcriptional activity." (PMID 31509973, 2019).
ovarian carcinoma (continued). "Calcitriol treatment significantly reduced both CD44+CD117+ and ALDH+ cells in this ovarian cancer cell line, while knockdown of VDR blocked calcitriol-induced decrease of these cells, indicating that the depletion of CSCs by calcitriol treatment is a VDR-dependent event." (PMID 29581858, 2018). "The vitamin D receptor (VDR), which binds the biologically active form of vitamin D (1,25-dihydroxyvitamin D [1,25(OH)D]), is weakly to moderately expressed in normal ovarian cells and more strongly expressed in many ovarian cancer cells lines and tumor tissues." (PMID 25368842, 2014). "Ovarian cancer, especially HGSC, showed a significantly higher expression of CD44 and VDR (p < 0.05) compared to atypical proliferative tumors and benign tumors." (PMID 40332380, 2025). "A moderate positive correlation was found between CD44, CD133, and VDR in all groups, with significant correlations with tumor grade and FIGO stage in ovarian cancer (p < 0.05)." (PMID 40332380, 2025). "VDR induces PD-L1 expression in AML and ovarian cancer cells: Calcitriol treatment induced upregulation of PD-L1 in primary AML (AML-1 and AML-2) cells." (PMID 37444542, 2023). "Of note is the use of 1,25-dihydroxyvitamin D3 (1,25D), the biologically active form of vitamin D which activates the vitamin D receptor (VDR), which has been reported to abrogate a stemness phenotype in ovarian cancer cells." (PMID 35203491, 2022). "Both WB and immunofluorescence (IF) analyses showed expression of VDR, RORγ, and RORα in OVCAR-3 and SKOV-3 ovarian cancer cells, with the latter showing significantly stronger levels of expression." (PMID 33227893, 2020). "For the ovarian cancer cell line, OVCAR-3, 1a,25(OH)2D reduces the proliferation induced by dihydrotestosterone through the VDR." (PMID 26000308, 2015). "Additionally, vitamin D status of study participants may modify associations between VDR genetic variants and cancer risk, which has not yet been explored for ovarian cancer." (PMID 25368842, 2014). "For the ovarian cancer cell line, OVCAR-3, 1α,25-(OH)2D reduces the proliferation induced by dihydrotestosterone through the VDR." (PMID 23826116, 2013). "There were significantly higher levels of CD44, CD133, and VDR expression in HGSC than in non-HGSC ovarian cancers (p = 0.015, p = 0.035, and p = 0.001, respectively)." (PMID 40332380, 2025). "A reduced level of vitamin D receptor (VDR) and an induced level of COX-2, 15-PGDH and PGE2 are found in the serum of ovarian cancer patients older than 45 years, suggesting an interaction between PG and vitamin D-metabolism in ovarian cancer." (PMID 32363546, 2020). "We then confirmed the involvement of VDR signaling in the inhibition of Wnt signaling by analyzing the TCF/LEF reporter activity with or without VDR in ovarian cancer cells." (PMID 29581858, 2018). "In particular, we discuss the influence of VDR-mediated signaling pathways in polycystic ovary syndrome (PCOS), gestational diabetes mellitus (GDM), preeclampsia, infertility and in vitro fertilization (IVF), endometriosis, and breast and ovarian cancer." (PMID 26000308, 2015). "The vitamin D receptor (VDR) upregulated the expression of TOPORS-AS1 while hnRNPA2B1 (heterogeneous nuclear ribonucleoprotein A2B1) directly interacted with TOPORS-AS1, both of which elicit the inhibition of β-catenin and suppress the proliferation of ovarian cancer cells." (PMID 40732992, 2025). "LXR, PXR, VDR or CAR activation was shown to exert protective features against ovarian cancer, similar to BA-elicited effects suggesting that BAs may have a more profound role in protecting against ovarian cancer." (PMID 35429253, 2022). "In addition, DFS was not affected by VDR expression in ovarian cancer cells (not shown)." (PMID 33227893, 2020).
ovarian carcinoma (continued). "This derivative did not achieve cytotoxicity through its effect on VDR but through its effect on the insulin-like growth factor receptor (IGFR) and the tumour necrosis factor alpha (TNFα) receptor on ovarian cancer cells." (PMID 32024052, 2020).
psoriasis (57 papers, 2009 to 2025). An autoimmune condition characterized by red, well-delineated plaques with silvery scales that are usually on the extensor surfaces and scalp. "Genetic polymorphisms in the VDR, particularly the TaaI/Cdx-2 (rs11568820) single-nucleotide polymorphism (SNP), are associated with susceptibility to psoriasis and other immune-mediated dermatoses." (PMID 40681996, 2025). "Psoriasis trials in our dataset were predominantly linked to mechanisms involving vitamins or hormones, with the vitamin D receptor emerging as a key target in a couple of studies." (PMID 40777013, 2025). "Previous studies support the importance of VDR polymorphisms and their correlations with the severity of psoriasis." (PMID 39409006, 2024). "The frequencies of the Fok1, Apa1, Bsm1, Taq1 and rs4516035 polymorphisms of the VDR gene were assessed in 93 psoriasis patients." (PMID 35318513, 2023). "The most investigated types of VDR gene polymorphisms in psoriasis are rs11568820 (Cdx2), rs2228570 (FokI), rs731236 (TaqI), rs7975232 (ApaI), rs1544410 (BsmI), rs757343 (Tru9I), and rs4516035 (EcoRV)." (PMID 36686134, 2023). "Several studies have found an association between VDR gene polymorphisms and response to psoriasis treatment." (PMID 36686134, 2023). "Our study identified an association between the VDR gene polymorphisms, namely ApaI, and psoriasis in a given community of Saudi patients with psoriasis." (PMID 36686134, 2023). "In conclusion, to our knowledge, this is the first study of VDR gene polymorphism as a predisposing factor for developing psoriasis in Saudi Arabia." (PMID 36686134, 2023). "A meta-analysis showed that the vitamin D receptor (VDR)TaqI polymorphism was associated with psoriasis susceptibility in Caucasian populations." (PMID 35707771, 2022). "Not only the changes of the expression of VDR are probably linked to psoriasis but also VDR polymorphism." (PMID 35955731, 2022). "One study that analyzed if VDR gene polymorphisms are associated with psoriasis concluded that the rs7975232 allele was over-expressed in psoriasis patients compared to controls." (PMID 36077185, 2022). "Until now, five VDR polymorphisms, FokI, ApaI, BsmI, TaqI and TaaI/Cdx2, have been studied in psoriasis, with contradicting results." (PMID 34208603, 2021). "Summarizing, we examined the association between VDR gene polymorphisms and psoriasis in the Polish population." (PMID 34208603, 2021). "The distribution of the analyzed VDR gene polymorphisms in patients with psoriasis and controls were in correspondence with the Hardy-Weinberg equilibrium (p > 0.05 in all cases), showing that the analyzed groups were selected correctly." (PMID 34208603, 2021). "Many studies have been conducted to determine the association between VDR polymorphisms and psoriasis, but few have included patients with PsA." (PMID 33376592, 2020). "Nevertheless, no statistically significant conclusions between VDR rs1544410, rs2228570 and VDR rs731236 polymorphisms and psoriasis susceptibility were observed." (PMID 31623568, 2019). "Data from the “Turkish” subgroup containing two case-control studies indicated a potential genetic correlation between the VDR rs7975232 polymorphism and psoriasis susceptibility." (PMID 31623568, 2019). "Increased sample sizes are still needed to investigate the genetic relationship between different VDR polymorphisms and the response of psoriasis patients to drug treatments." (PMID 31623568, 2019). "Based on the currently available data, we conducted a series of overall meta-analysis and subgroup analysis to evaluate the genetic relationship regarding VDR rs7975232, rs1544410, rs2228570, and rs731236 polymorphisms and psoriasis susceptibility." (PMID 31623568, 2019). "Here, we investigated the possible role of VDR rs7975232, rs1544410, rs2228570, and rs731236 polymorphisms in the susceptibility to psoriasis disease." (PMID 31623568, 2019).
psoriasis (continued). "Third, conflicting conclusions regarding the potential role of VDR polymorphisms in the partial resistance of psoriasis patients to calcipotriol therapy were reported." (PMID 31623568, 2019). "Despite of this, we cannot exclude the VDR rs731236 polymorphism in the odds of psoriasis in the Caucasian population, the support of more case-control studies is required." (PMID 31623568, 2019). "Second, high heterogeneity between studies was detected in some analyses of VDR polymorphisms and psoriasis susceptibility." (PMID 31623568, 2019). "More case-control studies will be of assistance to us to further confirm the effect of the VDR polymorphisms on the psoriasis susceptibility in the Caucasian population." (PMID 31623568, 2019). "Subgroup analysis of “Caucasian” suggested that the VDR rs731236 polymorphism is linked to the risk of psoriasis in the Caucasian population under the recessive model, but not the allele, homozygote and dominant models." (PMID 31623568, 2019). "The potential slight genetic effect of VDR rs731236 polymorphism in the high susceptibility to psoriasis in the Caucasian population was masked by the adding of more sample size, and the utilization of BH correction of P-value." (PMID 31623568, 2019). "There are a total of thirteen case-control studies with 1654 cases and 1991 controls for the meta-analysis of the VDR rs7975232 polymorphism and psoriasis susceptibility." (PMID 31623568, 2019). "For instance, the rs7975232 polymorphism of VDR was reportedly associated with the psoriasis risks in the Korean population, Chinese population, or Turkish population." (PMID 31623568, 2019). "We observed the open questions of the association between the VDR polymorphisms and psoriasis susceptibility among different populations." (PMID 31623568, 2019). "Our approach has been to examine those genes for which genetic variations have been shown to confer risk for psoriasis as potential targets for VDR-mediated regulation." (PMID 29401702, 2018). "Several studies identified an association between polymorphisms of vitamin D receptor (VDR) and psoriasis susceptibility." (PMID 28176237, 2017). "The TaqI polymorphism (allele T) in VDR was associated with familial psoriasis in a Turkish population." (PMID 24069534, 2013). "VDR is indispensable for the normal biological function of vitamin D3, and its deficiency can exacerbate inflammation, increase cell proliferation, and promote psoriasis development." (PMID 37554338, 2023). "Several population-specific studies have shown that VDR polymorphisms are associated with psoriasis risk in Asian populations such as, for example, Koreans, Chinese or Turks, whereas the opposite conclusion has been found in European populations such as Italians and Croats." (PMID 37967075, 2023). "They suggested that disequilibrium in VDR gene expression or allelic frequencies could be a risk factor for the development of psoriasis." (PMID 36686134, 2023). "VDR gene variants have been linked to a variety of disorders, including psoriasis, systemic lupus erythematosus, breast cancer, prostate cancer, malignant melanoma, osteoarthritis, diabetes, primary hyperparathyroidism, and atherosclerotic coronary artery disease." (PMID 36686134, 2023). "Further analysis of VDR gene polymorphisms may help to obtain more information on their association with development of psoriasis and different responses to phototherapy." (PMID 34208603, 2021). "Interestingly, several studies identified an association between polymorphisms of vitamin D receptor (VDR) and psoriasis susceptibility." (PMID 34067151, 2021). "Additionally, our study provides data for comparison with other studies to determine the possible value of VDR polymorphisms to predict predisposition to psoriasis in different ethnic groups." (PMID 34208603, 2021). "Our results suggest that VDR is a susceptibility factor for psoriasis development." (PMID 34208603, 2021).